APP (amyloid beta precursor protein)
Diseases named in the same sentence as APP in open-access papers (continued):
Sharing a sentence is not in itself a finding about the gene and the disease.
amyloid (continued). "Our studies in APP/PS1 mice give insight into the complexity of microglial activation and proliferation that are particularly relevant to early amyloid pathogenesis." (PMID 31822279, 2019). "This was observed in hippocampus from AD patients but also in APP/PS1 mice, an amyloid mouse model of AD." (PMID 30885273, 2019). "Increased amyloid plaque and Aβ levels, along with decreased IDE activity, were found in diet-induced insulin resistance APP transgenic mice." (PMID 29556189, 2018). "To model AD, we used the well-validated hTau and PSAPP(APP/PS1) mouse models that develop age-related tau and amyloid pathological features, respectively, and our well-established model of r-mTBI in C57BL/6 mice." (PMID 30618712, 2018). "HT can improve the learning and memory function of APP/PS1 transgenic mice by improving synaptic function and reducing amyloid plaque deposition." (PMID 29843688, 2018). "APP/PS1 mice were structured based on Aβ pathology, learning-memory deficits accompanied by detectable cerebral Aβ at 4 months, significant amyloidosis at 6–7 months, and further aggravates pathology at 10 months." (PMID 30687079, 2018). "This APP/PS1 animal model has been widely used in studies of neurological disorders of the brain, specifically AD, amyloid plaque formation, and aging." (PMID 30428894, 2018). "In cell lines and APPSWE/PSENdE9 (APP/PS1) transgenic mice, TSG suppresses APP–KPI+ and amyloid plaque formation." (PMID 30524653, 2018). "Systemic injection of rIL-33 in APP/PS1 mice reverses synaptic plasticity impairment and memory deficits with reduced soluble Aβ levels and amyloid plaque deposition." (PMID 30515150, 2018). "Gd-stained MRI was performed on five mouse models of amyloidosis (APPSL/PS1M146L, APP/PS1dE9, APP23, APPSwDI and 3xTg) and C57Bl/6 amyloid-free control animals." (PMID 28694463, 2017). "We assessed the amyloidosis changes by YXQN administration, and also detected the proteases involved in the proteolytic process of APP, including ADAM10, BACE1, and PS1, in order to develop the potential Chinese medicine for AD treatment." (PMID 28603494, 2017). "Our analysis reveals that Aβ4–x is restricted mainly to amyloid plaque cores and CAA in AD and DS cases, as well as in the 5XFAD and APP/PS1KI transgenic mouse lines of AD." (PMID 28978359, 2017). "In both AD and APP transgenic mouse brains, BACE1 accumulates in swollen presynaptic dystrophic neurites that surround amyloid plaques in close proximity." (PMID 26993139, 2016). "In horizontal brain sections of 10- and 16-month-old APP/PS1 and rTgTauEC x APP/PS1 mice, we immunolabeled plaques using the anti- Aβ antibody AW7 and determined amyloid plaque number and size in both the EC and the somatosensory cortex." (PMID 25853174, 2015). "We crossed rTgTauEC transgenic mice that demonstrate spread of tau from entorhinal cortex to other brain structures at advanced age with APP/PS1 mice, and examined mice with either NFTs, amyloid pathology, or both." (PMID 25853174, 2015). "In conclusion, EGCG treatment activated the TrkA signaling, inhibited the p75NTR signaling, and adjusted the TrkA/p75NTR imbalance by increasing the NGF relative expression in APP/PS1 mice to ameliorate the behavioral deficits and amyloidosis." (PMID 24356899, 2014). "Yet a previous study has shown that blocking astrocyte activation via AAV-Gfa2 vectors in APP/PS1 mice also attenuates microglia activation, improves cognitive and synaptic function and reduces amyloid load." (PMID 24490742, 2014). "In the brains of AD patients and APP/PS1 transgenic mice, amyloid plaques are surrounded by activated microglia and reactive astrocytes." (PMID 25386946, 2014). "In both the frontal cortex and hippocampus, we found a 50% to 60% reduction in parenchymal amyloid and over double the amount of CAA in the HHcy APP/PS1 mice relative to the control APP/PS1 mice (P < 0.01)." (PMID 24991237, 2014).
amyloid (continued). "Supportive evidence was also emerged from the transgenic APP/PS1 mouse model of AD, in which hyper-accumulated Aβ-42 residues lead to the early appearance of amyloid plaque formation when compared to mice with only the single transgene APP." (PMID 25161608, 2014). "Because CDK5 phosphorylates tau, APP, and BACE1, a component of the beta-secretase, CDK5 is an important link between amyloid- and tau-pathology." (PMID 23776568, 2013). "Using established behavioral tests that reveal deficits in APP transgenic models, BRI2-Aβ1-42 mice showed completely intact cognitive performance at ages both pre and post amyloid plaque formation." (PMID 23663320, 2013). "Nonetheless, our study demonstrated that FC was affected in several brain regions of APP/PS1 mice, at an age when amyloid pathology was present in the entire brain." (PMID 24358348, 2013). "Future studies should longitudinally evaluate APP/PS1 transgenic mice and correlate the rsfMRI findings to specific stages of amyloid pathology." (PMID 24358348, 2013). "In this research we utilize a transgenic murine model of AD, the APP/PS1 mouse, which bears a marked forebrain amyloidosis while hindbrain structures, including the cerebellum, are devoid of fibrillar Aβ plaques." (PMID 22511962, 2012). "Recent studies focused on the relationship between cholesterol level and amyloid precursor protein (APP) processing, trying to explain amyloidosis with elevated Aβ peptide generation." (PMID 23049991, 2012). "Double immunofluorescence revealed that, in the cortex and hippocampus of the APP/PS1 tg mice, the Hb-β+ plaque-like structures co-localized with Aβ+ amyloid plaques." (PMID 22412990, 2012). "Injection of LPS into the brain parenchyma of aged APP/PS1 mice originally aimed at stimulating the autotoxic loop resulted in microglial activation and the rapid reduction of amyloid deposits in the brain." (PMID 22844636, 2012). "Further investigation into the underlying mechanisms revealed that SV2A, as a binding protein of APP, could reduce amyloidosis of APP by inhibiting the binding of BACE1 to APP and regulating the intracellular distribution of APP." (PMID 41521688, 2026). "The 3xTg-AD model combines mutations in APP, PS1, and tau, exhibiting both amyloidosis and tauopathy, though it does not fully replicate human AD neurodegeneration or microglial/inflammatory responses." (PMID 40143845, 2025). "Sexual dimorphism in APP/PS1-associated pathology is manifested not merely in the difference in the total plaque burden, but in a qualitative difference in the nature of amyloidosis." (PMID 41300242, 2025). "The results showed that the 4‐month‐old APP/PS1 mice did not present with learning and memory loss and amyloid plaque deposition." (PMID 40047153, 2025). "The potential significance of NGF in amyloidosis arises from the fact that TrkA fails to interact with phosphorylated APP T668." (PMID 40387258, 2025). "Treatment with EGCG reduced the accumulation of amyloid plaques in the brain and encouraged the processing of amyloid precursor protein (APP) through non-amyloidogenic pathways." (PMID 41009815, 2025). "In two different APP/PS1 strains, the 5xFAD model and our APP/TTA mice here, microbiome properties first diverged from WT coincident with or shortly before the expected onset of amyloid pathology." (PMID 38178148, 2024). "In APP(−/−) (APP null mouse) brains, Aβ seeds can exist without the occurrence of amyloidosis, but amyloidosis occurred when Aβ seeds were transferred to the brains of APP(+/+) mice." (PMID 39346788, 2024). "It reduced APP expression, while increasing ADAM 17 expression in the non-amyloidosis pathway." (PMID 39185459, 2024).
amyloid (continued). "In an APP/PS1ΔE9 mouse model expressing human APOE3 or APOE4, TREM2-deficiency increased plaque growth in the early stages of amyloidosis with a decreased microglial response, without affecting an overall level of plaque deposition." (PMID 38462606, 2024). "Nevertheless, amyloid plaque density was not different in the cerebral cortex, hippocampus, or subiculum of semaglutide-treated 12-month-old 5XFAD and APP/PS1 mice." (PMID 39216535, 2024). "Here, we found that vascular dysfunction occurs prior to the onset of amyloid pathology, and Aβ plaque deposits colocalize with endothelial cells in the hippocampus of the female but not male APP/PS1 mice." (PMID 38862757, 2024). "Our study found that early GA treatment for 12 weeks in the young APP/PS1 mice without amyloid depositing attenuated amyloid pathology and improved spatial learning and memory in the MWM and Y-maze tests." (PMID 38352237, 2024). "We observed a significant reduction in Aβ load in APOE/APP/PS1 mice during a relatively short intervention period, highlighting the potential potency and relevance of humanin P3S in APOE4 biology prior to onset of amyloidosis." (PMID 38520065, 2024). "The overexpression of SREBP-2 in APP/PS1 mice has been reported to exacerbate amyloid pathology and neuronal death, accompanied by a decline in cognitive abilities, while the inhibition of SREBP-2 alleviates amyloid burden in AD mice." (PMID 38627829, 2024). "On the other hand, contrary to the classical AD-related mouse models of amyloid pathology, human AD brains do not overexpress APP and intracellular Aβ levels, though readily present, are expected to be very low." (PMID 37198698, 2023). "As it relates to amyloid pathologies, WNT plays multiple roles in APP processing including regulating APP post-translational phosphorylation, altering cell surface APP levels and endocytosis, modulating APP endosomal trafficking and processing, and influencing Aβ degradation." (PMID 37190113, 2023). "We hypothesized that microglia-specific knock-out of miR-155 in the APP/PS1 mouse model of AD would lead to upregulation of anti-inflammatory profiles of microglia, reduced amyloid pathology, and therefore increased survival of the mouse model." (PMID 36879321, 2023). "In APP transgenic mice specifically overexpressing TFEB in hippocampal astrocytes, TFEB mainly localizes in the nuclei of astrocytes and enhances lysosome function, resulting in reduced Aβ levels and amyloid plaque load." (PMID 36184826, 2023). "SB treatment, which acts through inhibition of both class I and II HDACs, was shown to improve memory in APP/PS1 mice, to reduce amyloid burden in 5xFAD mouse model, and to restore learning behavior and enhance neurogenesis in PS1/2 cDKO mice, an Aβ‐independent mouse model of AD." (PMID 37358017, 2023). "Our results show that a curative treatment of four months in eight-month-old APP/PS1 mice with PEL24-199 restores short- and long-term spatial memory and decreases amyloid pathology and neuroinflammation in this transgenic lesional model of amyloid deposition." (PMID 36982363, 2023). "Similarly, intracranial stereotaxic injection of AAV‐TFEB in hippocampal neurons of APP/PS1 mice leads to a reduction of APP, Aβ production, and amyloid plaque load by accelerating flux of the endosome‐lysosome pathway." (PMID 36184826, 2023). "Human platelets are the largest source of circulating APP, and the blood APP cleavage pathway is close to the amyloidosis and non-amyloidosis pathway in the central nervous system (CNS)." (PMID 36774494, 2023). "Also, in the context of amyloidosis models mimicking EOAD in humans, the glymphatic transport of injected radiolabelled Aβ and inulin was greatly reduced in old APP/PS1 mice (12–18 months old), as revealed by ex vivo radioactivity." (PMID 36707887, 2023).
amyloid (continued). "Amyloid beta peptides are formed by proteolytic cleavage of the amyloid precursor protein (APP) (reviewed elsewhere) and aggregate not only in the brain as amyloid plaques but also in the wall of cerebral blood vessels, originating a condition known as cerebral amyloid angiopathy (CAA)." (PMID 36734880, 2023). "Therefore, we incubated brain sections from the APP/PS1 mouse model of AD with biotinylated BP and identified bound‐BP and amyloid plaques using anti‐biotin and anti‐Aβ immunostainings, respectively." (PMID 37415305, 2023). "Cultured hippocampal 5xFAD neurons at 10–13 days in vitro exhibit neither severe amyloid pathology, due to limited time to accumulate human APP and PS1 transgenes, nor detectable level of amyloids." (PMID 36499137, 2022). "We showed that transgenic mouse strains of either tauopathy or amyloidosis phenotype, exhibit widespread increases in lysine succinylation at 4 months of age, which is not exclusive to tau and APP but parallels the early appearance of these proteinopathies." (PMID 35013160, 2022). "Under high magnification, microglia with large soma and short processes colocalized with amyloid plaques (surrounding the core of the plaques) and microglial processes appeared to interact directly with the plaques in both APP/PS1 and APP/PS1/eNOS+/− mice." (PMID 35806318, 2022). "Moreover, treatment of APP/PS1 mice with antibodies against Aβ3-Xpyro-E3 ameliorates behavioral symptoms and decreases amyloid plaque numbers, which is likely due to FcR-mediated clearance by microglia." (PMID 36359817, 2022). "There is therefore a link between ApoE and Aβ that does not depend on their direct interaction but rather on the ability of the different isoforms of ApoE to modify the processing of APP through LRP8, thus representing a bidirectional bridge between cholesterol metabolism and amyloidosis." (PMID 36012187, 2022). "TFEB is highly expressed in glial cells, thus activation of TFEB in astrocytes induces Aβ clearance and attenuates amyloid plaque, and the microglial expression of TFEB facilitates fibrillar Aβ degradation through upregulation of lysosomal biogenesis in APP/PS1 mice." (PMID 35948663, 2022). "Tau exosomal release has been suggested to be correlated with neuronal activity and could also be another explanation for increased AT8-positive tau pathology in APP.PS1 animals, particularly near amyloid pathology in our study." (PMID 35546164, 2022). "Therefore, to determine if metabolic syndrome in mid-life is a risk factor for AD, we generated a comorbid AD mouse model by deleting Sirt3 gene globally in APP/PS1 mice, an Alzheimer’s transgenic mouse model with amyloid pathology." (PMID 36396721, 2022). "As expected, older APP-KINL-G-F mice exhibited more amyloid pathology than younger mice, as well as a lack of amyloid pathology in APP-KINL-NL mice at the timepoints evaluated." (PMID 35739575, 2022). "This is a recently developed transgenic mouse model of AD exhibiting amyloid β peptide (Aβ) amyloidosis and a neuroinflammatory response in an age-dependent manner without non-physiological amyloid precursor protein (APP) overexpression." (PMID 35387663, 2022). "Soluble Aβ was only detected in APP/PS1 transgenic mice at 2.5 and 3.5 months of age, while senile plaques were detected in the hippocampus of 7-month-old APP/PS1 mice, as shown by the specific emission of broad-spectrum blue violet excitation light from amyloid deposits." (PMID 35807406, 2022). "In this current study, we characterized APP knock-in (APP-KI) animals, that do not overexpress hAPP but still develop amyloid pathology to understand the influence of protein overexpression." (PMID 35739575, 2022). "In this present study, we have characterized both the pathological and neurophysiological implications of seeding tau pathology in the APP-KI animal model with and without amyloid pathology, that does not exhibit APP overexpression." (PMID 35739575, 2022).
amyloid (continued). "Since the activation of DAPK1 function could contribute to the amyloidogenic processing of APP and the hyperphosphorylation of tau 44, DAPK1 may serve as an important therapeutic target for the simultaneous control of both amyloidosis and tauopathy in AD." (PMID 35002518, 2022). "Recent studies in APP/PS1/NLRP3-KO mice have shown a strong reduction of Aβ deposition, correlating with a high phagocytic capacity of microglial cells for the clearance of amyloid deposits." (PMID 35628216, 2022). "Amyloid plaques are extracellular deposits of the amyloid beta (Aβ) protein, which is generated from sequential proteolytic cleavage of its precursor called APP (amyloid precursor protein)." (PMID 36143299, 2022). "As expected, clustered formations became random closer to amyloid plaques in both Nr3c1+/+-APP/PS1 and Nr3c1ki/ki-APP/PS1 genotypes (P < 0.05); clustered eliminations were random in the proximal and intermediate zones except for Nr3c1ki/ki-APP/PS1 mice (P = 0.04)." (PMID 35733193, 2022). "Moreover, in the lesioned APP/PS1 cohort, the degree of amyloid pathology and inflammation were significantly reduced by the daily high-oxygen treatment." (PMID 36323689, 2022). "It is well known that APP-based transgenic mice recapitulate the amyloid pathology without NFT formation." (PMID 33644757, 2021). "The results highlight that Aβ-Teffs drive amyloidosis in the APP/PS1 mice brain via aberrant APP cleavage without affecting APP production." (PMID 34798897, 2021). "In vivo MRI using T1 and T2 scans and histological evaluation has identified differences in the entire brain or regional brain volumes between amyloidosis animal models and wild-type littermates, including APP T714I, APP/PS1, APP/PS1 KI, 3 × Tg, and TASTPM mice and McGill-R-Thy1-APP rats." (PMID 34884573, 2021). "Although the role of DAPK2 in amyloidosis in unknown, another family member, DAPK1, promotes the phosphorylation and amyloidogenic processing of APP." (PMID 30361487, 2021). "Given the presence of other microglial subtypes in WSB.APP/PS1 mice, these data suggest DAM may be specific determinants of the balance between parenchymal- and vascular-based amyloid." (PMID 33567283, 2021). "Under the action of different secretory enzymes in nerve cells, APP can undergo two different cleaving pathways, including the amyloidosis pathway and non-amyloidosis pathway." (PMID 34830326, 2021). "IL-33 can reverse the synaptic plasticity damage and memory deficits in APP/PS1 mice, and its mechanism may be to promote the differentiation of microglia into an anti-inflammatory phenotype and reduce soluble Aβ levels and amyloid plaque deposition." (PMID 33854693, 2021). "Amyloid precursor protein (APP) is a single-pass transmembrane protein with a wide extracellular domain, best recognized as the precursor molecule as its proteolysis produces amyloid-β (Aβ), the predominant component of the amyloid plaques identified in AD." (PMID 34940418, 2021). "Seeding of transgenic APP mice that do not develop amyloid plaques (HuAPPwt) has also been demonstrated using human amyloid-positive donor brain tissue." (PMID 33588898, 2021). "However, the APP/PS1 mice treated with MN‐08 and memantine in the prevention study had obviously attenuated amyloid plaque burdens." (PMID 33955647, 2021). "The effect of amyloid pathology on node of Ranvier length does not appear to be the result of altered axon diameter, as axon diameter was similar in WT and APP transgenic mice." (PMID 32557778, 2020). "For all behavioral and histological analysis we tested the mice at an average age of 6.5 months when amyloid pathology is readily detectable in mice expressing either APOE isoform and we previously have shown significant cognitive differences between APP/E3 and APP/E4 mice." (PMID 32703241, 2020).